CD46 (CD46 molecule)
Diseases named in the same sentence as CD46 in open-access papers (continued):
Sharing a sentence is not in itself a finding about the gene and the disease.
Allergy (3 papers, 2017 to 2025). An allergy is an immune response or reaction to substances that are usually not harmful. "CD46, a negative regulator of complement, has also been shown to protect against allergy." (PMID 40309766, 2025).
chronic obstructive pulmonary disease (3 papers, 2011 to 2024). A chronic and progressive lung disorder characterized by the loss of elasticity of the bronchial tree and the air sacs, destruction of the air sacs wall, thickening of the bronchial wall, and mucous accumulation in the bronchial tree. "CD46 encodes a regulatory protein for which higher expression in the lungs of ex-smokers appears to reduce inflammation and protect individuals from emphysema and chronic obstructive pulmonary disease." (PMID 27467526, 2016). "Also, there was a significant association among decreased CD46+ cells with decreased CD4+T cells, apoptosis mediator CD95 and increased CD8+T cells that were protecting patients without emphysema or severe chronic obstructive pulmonary disease." (PMID 21573156, 2011).
emphysema (3 papers, 2011 to 2022). "This has been proven in humans, where loss of lung function in patients with COPD and emphysema was associated with a lower expression of CD46." (PMID 36611613, 2022). "In contrast, CD46 down regulation was associated with decreased FEV1%, decreased expression of CD95 and CD4+ T cell depletion concomitantly with CD8+T cells increase in lung parenchyma of emphysema/COPD patients." (PMID 21573156, 2011).
end stage renal disease (3 papers, 2019 to 2023). "If complement inhibition is not applied within 4–5 relapses after MCPggaac haplotype onset, with/without adjacent mutations (CHF, CD46, C3), proteinuria, renal damage, and eventually chronic renal failure will occur." (PMID 37685848, 2023).
geographic atrophy (3 papers, 2017 to 2023). "One of the earliest changes in the retina of AMD patients is the loss of CD46 expression in the retinal pigment epithelial (RPE) cells in the course of geographic atrophy." (PMID 29093709, 2017). "CD46, a regulator of C3, is decreased in geographic atrophy, and its decrease can occur before identifiable AMD changes." (PMID 37366063, 2023). "The importance of the complement regulatory CD46 is demonstrated by the finding that retinal pigment epithelial (RPE) cells lose their CD46 expression very early in the development of geographic atrophy even before any morphological change of RPE." (PMID 29093709, 2017). "Retinal pigment epithelial CD46 expression is altered early on in geographic atrophy development." (PMID 33362763, 2020).
liver cancer (3 papers, 2016 to 2021). An epithelial or non-epithelial malignant neoplasm that arises from the liver. "In line with the variables’ acute prognostic effects, we determined a significant association between the levels of the variables, without CD46, in human liver cancer tissues." (PMID 34208132, 2021). "Given this significant correlation between levels of TIPRL, LC3 and CD133 in HCC tissues, we investigated and observed significant reductions in TIPRL, LC3, ATG7, CD133 and CD46 mRNA levels in HCC/liver cancer cell-lines transfected with two different small interfering RNA against TIPRL (siTIPRL)." (PMID 31727942, 2019). "Given the variables’ relationship with the OS of liver cancer patients, we further examined the roles of all five variables, TIPRL, LC3 (ATG7), CD133, CD44, and CD46, in normal liver (Chang), HCC (huh7), and iCCA (SNU1097) cell lines." (PMID 34208132, 2021). "Furthermore, our data showed a significant hazard ratio (HR) of CD133 in both sets and LC3 and CD46 in the validation set in OS of liver disease patients, unlike the public DB containing only liver cancer patients." (PMID 34208132, 2021).
liver disease (3 papers, 1999 to 2024). "To this list, we recently added soluble CD46 (sCD46) release as a marker of hepatocyte stress caused by fat accumulation in steatotic liver disease." (PMID 39698100, 2024). "Here, we show that the variables TIPRL, LC3, CD133, and CD44 each, excluding CD46, are associated with liver disease patients’ survival." (PMID 34208132, 2021). "In contrast to many routine biochemical markers of liver disease, CD46 is expressed on almost all human cells." (PMID 39698100, 2024). "On the other hand, except for cirrhosis and liver tissue degeneration, we determined the upregulation of CD133, CD44, and CD46 in liver disease tissues." (PMID 34208132, 2021). "For the assessment, we stained tissues of human liver disease/cancer with antibodies against TIPRL/LC3/CD133/CD44/CD46, followed by confocal observation." (PMID 34208132, 2021). "Considering these differences, we further studied the association between disease-specific survival (DSS) of liver disease patients and the levels of four variables without CD46." (PMID 34208132, 2021). "Contrarily, we discovered the upregulation of CD133, CD46, and CD44 in liver disease tissues, except for cirrhosis." (PMID 34208132, 2021).
lung adenocarcinoma (3 papers, 2013 to 2019). A carcinoma that arises from the lung and is characterized by the presence of malignant glandular epithelial cells. "Furthermore, examination of data in the Cancer Genome Atlas (TCGA) reveals gene amplification or increased expression of the complement regulatory proteins, CD46 and CD55, in approximately 25% of human lung adenocarcinomas." (PMID 31134065, 2019). "Furthermore, examination of data in the Cancer Genome Atlas (TCGA) reveals gene amplification or increased expression of complement regulatory proteins, CD46 and CD55 in ~25% of human lung adenocarcinomas." (PMID 31134065, 2019). "Interestingly, CD46 expression analysis was not sufficient to predict the infection levels of some lung adenocarcinoma cell lines." (PMID 23586034, 2013).
lung carcinoma (3 papers, 2016 to 2024). "To test this hypothesis, we incubated A549 lung carcinoma cells with increasing concentrations of recombinant fiber knob from adenovirus type 16 (16 FK), a species B adenovirus previously shown to use CD46 as a receptor." (PMID 39772136, 2024). "Increased expression of CD55, CD46 and CD59 has been documented in lung cancer cells while another study showed increased factor H mRNA in lung cancer biopsies." (PMID 38178176, 2024).
lupus nephritis (3 papers, 2011 to 2018). Glomerulonephritis in the context of systemic lupus erythematosus. "In contrary to pervious study which analyzed the correlation of serum CFH and disease activity of patients with lupus nephritis, our study demonstrated that only serum CFI but not CFH and CD46 correlated statistically with SLEDAI scores." (PMID 29492211, 2018).
nephritis (3 papers, 2011 to 2022). Inflammation of renal tissue. "The median age of nephritis onset in the SLE patients carrying CD46 and CFH mutations in the combined cohorts was 24 years (range 12 to 51) compared with 32 years (range 9 to 84) in the patients free of the mutations." (PMID 22171659, 2011). "The A353V polymorphism, known to affect function of CD46, was found in 6.6% of nephritis patients versus 4.9% and 6.1% of the non-nephritis SLE patients and controls." (PMID 22171659, 2011). "Furthermore, we found weak indications that there is one protective and one risk haplotype predisposing to nephritis composed of several polymorphisms in noncoding regions of CD46, which were previously implicated in aHUS." (PMID 22171659, 2011). "Mutations found in CD46 and CFH were found to affect the age at onset of nephritis in the analyzed SLE patients." (PMID 22171659, 2011). "Analysis of all CD46 exons in 196 patients with nephritis (southern Sweden, n = 43; mid Sweden, n = 153) revealed three nonsynonymous mutations in the coding exons." (PMID 22171659, 2011). "In the present study we performed Sanger sequencing of all exons in the CD46 and CFH genes in two cohorts of SLE patients collected in southern and mid Sweden to identify rare variants with a potential effect on SLE and SLE nephritis." (PMID 22171659, 2011). "In their study, they found that mutations in CFH and CD46 were not as common as in aHUS; however, these mutations were associated with earlier onset of nephritis." (PMID 36211394, 2022). "Potential association of FH autoantibodies with nephritis would be of particular interest to study further due to recently reported genetic association with FH polymorphisms and SLE, as well as association with non-synonymous mutations in FH and CD46 with faster onset of nephritis in SLE patients." (PMID 22894814, 2012). "The exons of complement inhibitor genes CD46 and CFH (factor H) were fully sequenced using the Sanger method in SLE patients with nephritis originating from two cohorts from southern and mid Sweden (n = 196)." (PMID 22171659, 2011). "Taken together, SLE and SLE nephritis do not appear to be associated with frequent mutations in CD46 or CFH as reported for some other kidney diseases, but these mutations are likely to affect the year of onset of nephritis." (PMID 22171659, 2011). "The presence of mutations in CD46 and CFH did not predispose to SLE or nephritis but was associated with earlier onset of nephritis." (PMID 22171659, 2011).
oral squamous cell carcinoma (3 papers, 2025). "In oral squamous cell carcinoma (OSCC), CD46 shows markedly high expression with diffuse strong positivity on tumor cell membranes/cytoplasm, TREM1 is overexpressed, and LC3B/ATG5 expression is low." (PMID 41415031, 2025).
ovarian tumour (3 papers, 2002 to 2021). "Complement‐mediated cell killing of breast, lung and ovarian tumour cells by combined trastuzumab and pertuzumab was previously shown to be efficient only when all three CD46, CD55 and CD59 mCRPs were suppressed using the siRNA gene silencing technology." (PMID 31365168, 2019).
age-related macular degeneration (2 papers, 2014 to 2017). Age-related loss of vision in the central portion of the retina (macula), secondary to retinal degeneration. "Based on these observations, it is postulated here that similar HHV-6A/CD46/complement interactions are central in the development of age-related macular degeneration (AMD)." (PMID 29093709, 2017).
allergic asthma (2 papers, 2018 to 2024). A asthma with a basis in a pathological type I hypersensitivity reaction. "Taken together, these results suggest that CD46 could induce autophagy and decrease oxidative stress-mediated apoptosis in respiratory epithelium, and this may offer a new potential therapeutic strategy to treat allergic asthma." (PMID 30154478, 2018).
anemia (2 papers, 2013 to 2024). A reduction in the number of red blood cells, the amount of hemoglobin, and/or the volume of packed red blood cells. "The CD46/Townes mice model resembles SCD in several key disease characteristics, such as leukocytosis, sickled RBCs, anemia, insufficient hemoglobin levels, high reticulocyte count, and splenomegaly." (PMID 39489920, 2024).
atherosclerosis (2 papers, 2017 to 2025). A disease characterized by the build-up of fatty material and calcium deposition in the arterial wall resulting in partial or complete occlusion of the arterial lumen. "It is noteworthy to mention that endothelial cell dysfunction is an important hallmark in atherosclerosis and it was previously reported that CD46 protein level was found to be up-regulated in atherosclerotic plaque." (PMID 28199366, 2017). "Additionally, the inflammatory milieu, characterized by elevated production of cytokines and altered expression of CD81 and CD46, aligns with previous findings that associate these markers with the pathogenesis of atherosclerosis and IHD55,56." (PMID 39975917, 2025).
bacteremia (2 papers, 2011 to 2021). "Transgenic mice expressing human CD46, a proposed adhesion receptor for N. meningitidis, and infected with a ΔpilT mutant displayed a reduced bacteremia and a higher survival rate compared to the WT strain." (PMID 33592056, 2021).
breast tumors (2 papers, 2016 to 2021). "Namely, in primary breast tumours the expression of factor I and CD46 correlated with larger tumour size, lower differentiation index, and poor prognosis." (PMID 33658651, 2021). "Using tissue microarray, strong CD46 expression was exhibited by 27% of the breast tumors." (PMID 27203670, 2016).
common variable immunodeficiency (2 papers, 2015 to 2023). "Of the ~ eight known aHUS cases of homozygous CD46 deficiency, three also developed common variable immunodeficiency." (PMID 26054645, 2015). "Further, a subset of CD46-deficient patients develops common variable immunodeficiency (CVID), a syndrome characterized by hypogammaglobulinemia." (PMID 26054645, 2015). "None of the CD46 mutation carriers displayed an overt antibody deficiency in circulation although it has been reported that individuals with homozygous CD46 mutations have common variable immunodeficiency (CVID)-like immunodeficiency." (PMID 37477760, 2023).
dense deposit disease (2 papers, 2021 to 2024). "Further identified heterozygous polymorphisms in the patient included the CFH Y402H risk factor for dense deposit disease, as well as the CD46 rs2796267, rs2796268 and rs1962149 polymorphisms, referred as part of the MCPggaac risk haplotype for aHUS." (PMID 34248927, 2021).
encephalitis (2 papers, 2021 to 2024). An acute inflammatory process affecting the brain parenchyma. "The discovery of the measles virus (MV) receptor CD46 allowed the development of an MV-encephalitis mouse model using transgenic mice expressing human CD46 under the control of a neuronal promoter." (PMID 38997413, 2024). "Human CD46 mediates progressive viral dissemination and the development of encephalitis." (PMID 34408631, 2021).
febrile seizures (2 papers, 2015 to 2020). "Two SNPs in two genes associated with MMR-related febrile seizures were identified: IFI44L (rs273259: P = 5.9 × 10−12 vs. controls; P = 1.2 × 10−9 vs. MMR-unrelated febrile seizures) and CD46 (rs1318653: P = 9.6 × 10−11 vs. controls; P = 1.6 × 10−9 vs. MMR-unrelated febrile seizures)." (PMID 33167413, 2020).
head and neck squamous cell carcinoma (2 papers, 2021 to 2025). A squamous cell carcinoma that arises from any of the following anatomic sites: lip and oral cavity, nasal cavity, paranasal sinuses, pharynx, larynx, and salivary glands. "For example, head and neck squamous cell carcinoma (HNSCC) cells express significantly elevated levels of CD46, CD55 and CD59, when compared to benign keratinocyte cells." (PMID 33802004, 2021). "The expression levels of complement regulatory proteins CD46, CD55, and CD59 are notably elevated in various tumors, including head and neck squamous cell carcinoma (HNSCC), colon cancer, renal cancer, lung cancer, and breast cancer." (PMID 39958348, 2025).
hemoglobinopathies (2 papers, 2022 to 2025). "Our goal was to test HDAd5/35++ vectors for gene therapy of hemoglobinopathies based on promising studies performed in CD46-transgenic mouse models for thalassemia and sickle cell disease." (PMID 35036470, 2022). "While we have demonstrated safety and efficacy of the in vivo approach in CD46-transgenic mice and rhesus macaques, studies in mice with a humanized hematopoietic system could facilitate its potential clinical translation for the treatment of hemoglobinopathies and HIV." (PMID 40231246, 2025).
Hepatic steatosis (2 papers, 2024). Steatosis is a term used to denote lipid accumulation within hepatocytes. "In humans, soluble CD46 (sCD46) levels in blood were recently identified as an accurate biomarker of hepatic steatosis." (PMID 39698100, 2024).
HIV-1 infection (2 papers, 2021 to 2022). The type species of lentivirus and the etiologic agent of acquired immunodeficiency syndrome (AIDS). "The SNP rs2796265 is located in the promoter region of CD46, and the alleles are correlated to mRNA levels and splicing isoforms ratio supporting a role in the pathogenesis of HIV-1 infection, as previously suggested." (PMID 34831317, 2021). "Our results suggest that CD46 has a role in innate resistance to HIV-1 infection, which supports the importance of complement receptors and regulators in the pathogenesis of HIV infection." (PMID 34831317, 2021). "If our results are confirmed, they may lead to a new potential target for pharmacological intervention in HIV-1 infection by modulation of CD46 signaling." (PMID 34831317, 2021). "Moreover, lymphocytes and dendritic cells from HIV-1 infected patients show significative lower levels of extracellular CD46 expression, indicative that CD46 may influence the pathophysiology of the HIV-1 infection." (PMID 34831317, 2021). "As such, we targeted the expression of five genes with roles in HIV-1 infection (CD4, CXCR4, PSGL-1, TRIM5α and CPSF6) as well as CD46, in part using gRNAs pre-tested for each target for the efficiency of editing and protein loss was assessed in part by confocal microscopy." (PMID 34949807, 2022).
Hypertension (2 papers, 2020 to 2023). The presence of chronic increased pressure in the systemic arterial system. "Of the 4 transplants in recipients with pathological variants in CD46, 1 graft failed 10-mo posttransplant from hypertensive donor disease." (PMID 36413152, 2023).
Infertility (2 papers, 2015 to 2022). "Variations in CD46 expression on sperm have been associated with infertility." (PMID 35286314, 2022).
metastatic melanoma (2 papers, 2020 to 2025). A melanoma that has spread from its primary site to another anatomic site. "It has been recently suggested that CD46 is the major BBB-associated receptor used by exosomes derived from metastatic melanoma cells for crossing the BBB." (PMID 32575812, 2020). "Recently, it was shown that the receptors CD46 and integrin α5 significantly contribute to the uptake of exosomes derived from Brain-Metastatic Melanoma Cells in the BBB." (PMID 40943171, 2025).